LINC02901 (long independently transcribed non-coding RNA 2901)
Synonyms: C6orf99; yR211F11.1
Gene: Long non-coding RNA gene on chromosome 6 (158,869,067 to 158,948,522, forward strand). Ensembl gene ENSG00000203711.
Diseases named in the same sentence as LINC02901 in open-access papers:
LINC02901 is named in the same sentence as 4 diseases in open-access papers, as found by Europe PMC text mining. Sharing a sentence is not in itself a finding about the gene and the disease.
LINC02901 shares sentences with these, for which no sentence is quoted: breast carcinoma (8 papers); cancer (2); tumor (2); liver cancer (1).